RNU7-77P (RNA, U7 small nuclear 77 pseudogene)
Synonyms: U7.77
Gene: Small nuclear RNA gene on chromosome 10 (35,135,443 to 35,135,502, forward strand). Ensembl gene ENSG00000253054.
Homologues: Orthologues: chimpanzee U7 (98% identical), macaque U7 (93% identical). Paralogues in human: RNU7-28P (92% identical), RNU7-18P (90% identical), RNU7-40P (90% identical), RNU7-7P (90% identical), RNU7-11P (88% identical), RNU7-13P (88% identical), RNU7-14P (88% identical), RNU7-25P (88% identical), RNU7-3P (88% identical), RNU7-45P (88% identical), RNU7-128P (87% identical), RNU7-22P (87% identical), and 143 more.